SSTR2 (somatostatin receptor 2)
Diseases named in the same sentence as SSTR2 in open-access papers (continued):
Sharing a sentence is not in itself a finding about the gene and the disease.
tumor (continued). "This latter property renders SSTR2 a potential target for intracellularly delivering cytotoxic and other growth suppressive agents to tumor cells." (PMID 31091786, 2019). "Beyond symptomatic management, recent research demonstrates that SSAs exert antiproliferative effects and inhibit tumor growth via the somatostatin receptor 2 (SSTR2)." (PMID 31234481, 2019). "Both tumor lines maintained high expression of SSTR2 and all tumor groups saw delayed tumor growth and higher survival over controls." (PMID 31779154, 2019). "One potential approach to address this issue is theragnostic based tumor imaging to assess SSTR2 positivity." (PMID 31413814, 2019). "It was demonstrated that SSTR2 expression at the membrane of tumor cells was co-expressed with markers of poor prognosis." (PMID 31569719, 2019). "Incorporation of SSTR2 into the lentiviral vector demonstrated the value of T cell imaging for prediction of tumor response and possibly toxicity indicated by off-tumor expansion of CAR T cells." (PMID 31337787, 2019). "Immunostaining of somatostatin receptor (SSTR)-2, which is overexpressed in well-differentiated NENs, showed the presence of a membranous pattern of staining in less than 50% of tumor cells (score 2)." (PMID 31511024, 2019). "They found that in the subset of NFPTs in which DRD2 or SSTR2 agonists inhibited bulk tumor cell proliferation, the antiproliferative effect was maintained in the corresponding spheres." (PMID 31708878, 2019). "This is due to the high affinity of the radiolabeled compound for the SSTR type 2 (SSTR2) that can more accurately predict a tumor response to treatment to radiolabeled somatostatin analogs in patients with avidity for the tracer." (PMID 30538672, 2018). "SSTR-2 levels in several tumor cell lines are negatively correlated with the DNA methylation status in its promoter region, and the DNA methylase inhibitor 5-aza-deoxycytidine up-regulates SSTR-2 expression." (PMID 30038293, 2018). "SSTR-2 expression was determined on original patient tumours and 3D cultures of three established cultures." (PMID 29858948, 2018). "In GOT1 and BON-1, we also found expression of SSTR2, a major target for symptomatic treatment of hormonal symptoms, tumour imaging and peptide receptor radiotherapy in GEPNET patients." (PMID 29444910, 2018). "SSTR-2 expression was determined on original patient tumours and 3D cultures of the three established cultures." (PMID 29858948, 2018). "It is also important to note that all receptor-positive tumor samples expressed a well-detectable amount of the SSTR-2 or SSTR-5 receptor gene." (PMID 29949880, 2018). "A second-generation of SSTR2 antagonists that include DOTA-JR11 showed higher tumor uptake when combined with 68Ga-DOTA (1.3 times), or 68Ga-NODAGA (1.7 times) as compared with DOTA analogs." (PMID 30538672, 2018). "A nearly absolute growth inhibition and reduction in tumor volume was observed following 40 days long treatment with SSTR2 pep-DIM-NP whereas untreated group showed larger size of tumor." (PMID 29029435, 2017). "In PET images of mice bearing SSTR2-positive tumours administered [68Ga(THP-TATE)], tumours can be clearly delineated." (PMID 28075350, 2017). "We also determined that SSTR2 expression was correlated with the short-term biochemical and tumor volume response to SSA." (PMID 28396686, 2017). "Tumor regions with a high number of SSTR2-positive cells corresponded to focal areas of increased radioactivity." (PMID 29097943, 2017). "The tumor stained positively with several neuroendocrine markers including chromogranin A, synaptophysin and somatostatin receptor-2." (PMID 28378747, 2017). "From the six paired samples analyzed, two cases showed specific binding of the GRPR and SSTR2 radioligands in both the primary tumor and the lymph node metastases." (PMID 28107508, 2017). "With a low dose of 177Lu-DOTA-TATE (20 MBq/animal), tumor growth inhibition was achieved in the CHLA-15 high SSTR2 expressing xenograft model." (PMID 29097943, 2017).
tumor (continued). "Both 213Bi and 111In form highly stable complexes with DOTA-somatostatin analogs, including DOTATATE, and show similar affinities for SSTR2 in tumor." (PMID 27873240, 2016). "Both tumours have relatively high SSTR2 expression, and both have often been applied as a model in preclinical studies of PRRT in NET." (PMID 26791386, 2016). "Our results showed that SSTR2 promoter methylation levels in cancer tissues were significantly higher than in the paired non-tumor tissues (5.80 ± 3.87 % versus 3.67 ± 3.22 %, P = 0.001, adjusted P = 0.003)." (PMID 26796520, 2016). "It is therefore not surprising that DOTATATE, which has a predominant affinity for SSTR-2, is sensitive for imaging these tumours." (PMID 27535829, 2016). "213Bi-DOTATATE was effective in different neuroendocrine (H69 and CA20948) tumour models with overexpression of SSTR2 in mice." (PMID 26791386, 2016). "Two different tumour models with somatostatin receptor subtype 2 (SSTR2) expression were used: CA20948 (rat pancreatic tumour) and H69 (human small cell lung carcinoma)." (PMID 26791386, 2016). "Its efficacy depends on the radiation absorbed dose delivered to the tumor, which depends on SSTR2 targeting efficiency, clearance kinetics, perfusion, distribution, and tumor mass." (PMID 27873240, 2016). "SSTR2 mRNA expression was detected in tumor tissues in all experimental groups and was higher in each treatment group than in the control group." (PMID 27825139, 2016). "The rat AR42J tumor is known to express SSTR2 at high density; this model is commonly used for investigations using somatostatin analogs and PRRT." (PMID 27873240, 2016). "In this study, we compared the efficacy of 213Bi-DOTATATE TAT in tumours of different sizes in two different tumour models, both with expression of SSTR2." (PMID 26791386, 2016). "Underlying cause for the difference is possibly the specific targeting of octreotide to SSTR2, which is distributed at high density on tumor cell surface." (PMID 27825139, 2016). "Increased SSTR2 expression led to strong up-regulation of cyclin-dependent kinase inhibitor p16, which then inhibited tumor cell cycle progression from G1 to S phase." (PMID 26796520, 2016). "In vivo, [68Ga(THP-TATE)] clears rapidly from circulation, accumulates specifically at SSTR2-positive tumours and is cleared predominantly via a renal pathway." (PMID 26452495, 2015). "The biodistribution of [68Ga(THP-TATE)] was assessed in Balb/c nu/nu mice bearing SSTR2-positive AR42J tumours." (PMID 26452495, 2015). "RT-PCR assay has good specificity and high sensitivity for detection of SSTR-2 gene expression in tumor specimens." (PMID 25890201, 2015). "In our opinion, the potential influence of chemotherapeutics on tumour perfusion and SSTR2 expression is of major importance as well, to determine an optimal scheme for the combination of PRRT with chemotherapeutics." (PMID 26553049, 2015). "Animals administered [68Ga(THP-TATE)] demonstrated comparable SSTR2-positive tumour activity (11.5 ± 0.6 %ID g−1) compared to animals administered [68Ga(DOTATATE)] (14.4 ± 0.8 %ID g−1)." (PMID 26452495, 2015). "The inhibition mechanism involves the combined interaction of somatostatin and its analogs with SSTR-2 in tumor tissues, mainly through binding to tumor tissue receptors, which directly inhibits tumor cell proliferation." (PMID 25890201, 2015). "Researchers believe that the expression of SSTR-2 in tumor tissue is the premise for patients to accept somatostatin therapy." (PMID 25890201, 2015). "In fact, this antitumor effect has been demonstrated in experimental pancreatic tumors stably expressing SSTR2, or after therapeutic SSTR2 gene transfer with inhibited tumor growth." (PMID 25977882, 2015). "A representative example of immunostaining in one resected tumor sample is given in S3 Fig. (monoclonal and polyclonal anti-SSTR2-antibody)." (PMID 25807228, 2015).
tumor (continued). "Biodistribution of [68Ga(THP-TATE)] was compared with that of [68Ga(DOTATATE)] in Balb/c nude mice bearing SSTR2-positive AR42J tumours." (PMID 26452495, 2015). "In these cancers SSTR2 activation leads to an inhibition of tumor cell proliferation, mostly mediated via growth arrests." (PMID 25010045, 2014). "SSTR2 expression is differentially regulated in various tumor types and therapeutic somatostatin analogs binding to SSTR2 are in clinical use." (PMID 25010045, 2014). "Several studies have indeed suggested a role of SSTR2 in the regulation of tumor cell proliferation in various tumors, since tumors with reduced SSTR2 protein levels revealed increased cell proliferation." (PMID 25010045, 2014). "Immunohistochemical analysis showed that the tumor expressed SSTR2; staining was more intense on the periphery of the cells and showed weaker reactivity inside them." (PMID 25369268, 2014). "SSTR2 is widely and strongly expressed in nervous, endocrine, and tumor tissues, and most of the clinically available somatostatin analogs have a strong SSTR2-binding affinity." (PMID 24587133, 2014). "The patients treated with octreotide LAR showed a significantly higher mean survival rate, compared with controls, and patients’ survival was significantly correlated with SSTR2 messenger expression in the tumour." (PMID 25225571, 2014). "The same strong inverse correlation with SSTR2 staining intensity was detected with tumor cell proliferation as determined by Ki67 LI." (PMID 25010045, 2014). "The tumor samples that expressed SSTR2 above this cutoff were defined as having high SSTR2 expression and those that expressed SSTR2 below this level were defined as having low expression." (PMID 24137418, 2013). "The overexpression of SSTR2 has also displayed anti-tumor effects and significantly increased the sensitivity of SSTR treatment in a number of experimental SSTR-negative cancer cell lines and xenografts." (PMID 24137418, 2013). "Although, there is growing understanding for the synergistic effect of many GPCRs in cells transfected with one or more receptor, this is the first comprehensive description of SSTR2 and ORs in tumor cells expressing both receptor subtypes endogenously." (PMID 24059654, 2013). "SSTR2 expression in the tumor tissue was lower than in the surrounding cirrhotic liver tissues at a positive rate of 59.6% (59 of 99 cases) vs. 90.9% (90 of 99 cases; χ2, 26.06; P <0.001)." (PMID 24137418, 2013). "The response to SA depends on the presence and/or ratio of somatostatin receptor subtypes (SSTR1–5) on tumor cells; SSTR2, especially, has been positively correlated to the GH-lowering effect of hitherto clinically available analogs." (PMID 23825587, 2013). "The SSTR2 content in the tumor is a well-known contributor to the response to treatment, and we confirmed that increased SSTR2 mRNA expression is associated with a good response to the acute SA test." (PMID 23825587, 2013). "Univariate analysis indicated that the elevated mRNA levels of both SSTR2 and RORC were associated with a larger decrease in IGF-1 levels and tumor reduction." (PMID 23825587, 2013). "Positive immunostaining for SSTR2 and 5 was localized primarily to the cell membrane and cytoplasm of the cirrhotic liver cells and the tumor cells." (PMID 24137418, 2013). "Precisely, SSTR2 is expressed at remarkably higher levels in many tumor cells relative to normal tissues." (PMID 24287991, 2013). "Histological results showed that the xenograft tumours stained positive for anti-SSTR2 with some unspecific binding." (PMID 22214480, 2011). "In contrast, patients with gastro-entero-pancreatic tumours have been treated successfully with somatostatin analogues; furthermore, exogenous gene transfer of the SSTR2 gene into SSTR-negative tumours has enabled treatment with somatostatin analogues." (PMID 22214480, 2011).
tumor (continued). "The ITCC-octreotate conjugate exhibits fast receptor binding properties in SSTr-2-overexpressing RIN38/SSTr-2 cells and provides three-fold higher tumor fluorescence intensity in mice bearing RIN38/SSTr-2 tumors from 3 to 24 h after intravenous injection." (PMID 22180839, 2010). "It has higher affinity for SSTR2 and shows significant anti-neoplastic actions in tumours expressing SSTR2." (PMID 21143993, 2010). "It remains the drug of choice for application in a majority of pure NE tumours because such tumours predominantly express SSTR2." (PMID 21143993, 2010). "Here we observed a diminished or lost expression of SHP-1 and SSTR2, the two fundamental components of antiproliferative signal presents in prostate cells, and we demonstrate that this is consistent with advanced tumor grade." (PMID 19365586, 2009). "This conjugate selectively targets somatostatin receptor subtype 2 (SSTR2) and also retains high binding affinity and rapid internalization as well as anti-proliferative activity towards various tumor cells." (PMID 21892324, 2008). "Herein, the expression of mRNAs of all 5 SSTRs and protein of SSTR2 in 5 tested tumor cells were investigated by RT-PCR and western blot." (PMID 21892324, 2008). "Abundant SSTR2 mRNAs were detected in all 5 cultured tumor cells and SSTR2 proteins were detected as well." (PMID 21892324, 2008). "Our findings were related to WHO grade, tumor subtype, and SSTR2 immunoreactivity." (PMID 41769706, 2026). "SSTR2 antagonists have demonstrated superior tumor targeting." (PMID 41599769, 2026). "Distinctive morphological features, such as frequent tubular architecture, and a characteristic immunoprofile (common MUC1 positivity and rare SSTR2 A expression, in addition to somatostatin expression and tumor location), help to identify ampullary Som-NETs among NF-Duo-NETs." (PMID 40347392, 2025). "However, we expect that the radiation doses to bone marrow cells would be markedly lower than for SSTR2-expressing tumor cells despite comparable radioligand uptake." (PMID 40521188, 2025). "A local anti-tumor bystander effect was also observed after induction of mixed tumors containing an only 1:3 ratio of SSTR2 expressing to control cells in that tumor volume and incidence of metastases were significantly reduced already at day 13 post-implantation." (PMID 40134804, 2025). "However, when compared to the reference group (lactotroph tumours), all other tumour lineages exhibited greater odds of SSTR2 expression." (PMID 40770587, 2025). "Hence, in both primary and metastatic PDAC models, in vivo Sstr2 transfer induced a significant anti-tumor effect that resulted from a decrease in cell proliferation and an increase in apoptosis." (PMID 40134804, 2025). "The availability of a tumor-specific target (SSTR2) combined with advances in nuclear medicine has paved the way for theranostics, an approach that integrates molecular imaging and targeted radionuclide therapy to offer a more precise and effective treatment strategy." (PMID 40389624, 2025). "Therapeutically, these patients may also benefit from peptide receptor radionuclide therapy (PRRT) using 177Lu-DOTATATE, which delivers targeted beta-emitting radiation to SSTR2-expressing tumor cells." (PMID 41002582, 2025). "These pathways are known to contribute to tumor proliferation, immune evasion, angiogenesis, and metastatic potential in HCC, suggesting that SSTR2 may promote a more aggressive tumor phenotype through modulation of these signaling networks." (PMID 41002582, 2025). "Tumor origin offers additional stratification within NECs, while SSTR2 expression may inform targeted approaches." (PMID 41450443, 2025). "The action of the LA‐SSTA is exerted mainly through SSTR‐2 on the tumour cells." (PMID 39503166, 2025). "This suggests that SSTR2 may be upregulated during malignant transformation and could play a context-specific role in tumor biology." (PMID 41002582, 2025).
tumor (continued). "Recent studies have shown that HDAC inhibitors administered in NETs increase SSTR2 in the tumour." (PMID 41303787, 2025). "Hence, VEGF, tumor vascularization, and Sstr3 expression were identified as novel targets for the SSTR2-mediated anti-tumor bystander effect." (PMID 40134804, 2025). "IMPLICATIONS FOR PATIENT CARE: The results suggest that [212Pb]Pb-DOTAMTATE could potentially offer a more effective targeted α-therapy treatment option for SSTR2-positive NETs with a favorable tumor retention and dosimetry profile." (PMID 39884771, 2025). "The treatment-naïve primary tumor tissue exhibited a relatively high expression of SSTR2." (PMID 39324010, 2024). "The researchers used a virtual patient PK model to investigate tumor control probability with respect to tumor perfusion and SSTR2 density; the results indicated a minimum tumor perfusion of 0.062 mL/g/min and receptor density of 55 nmol/L to establish a 99% tumor control probability." (PMID 39649120, 2024). "The overexpression of somatostatin receptor type 2 (SSTR2) is a property of various tumor types." (PMID 38791956, 2024). "Notably, there is a difference in the genetic and epigenetic makeup of SSTR2 genes in some tumor cell lines." (PMID 39329930, 2024). "This event may contribute to a growth advantage of tumor cells and is consistent with findings that SSTR2 exhibits anti-tumor properties." (PMID 39682758, 2024). "SSTR2 was expressed in all the tumors, from 60% to 70% of the entire tumor area." (PMID 39055601, 2024). "The activation of SSTR2 inhibits the proliferation of tumor cells primarily through growth arrests." (PMID 37713112, 2024). "Notably, in the group derived from CFPAC-1 cells, which exhibited the highest SSTR2 expression levels, we observed a halt in tumor growth and actual tumor shrinkage." (PMID 38791582, 2024). "Sequential sections from each specimen were also stained with standard hematoxylin and eosin (H&E) and immunohistochemistry (IHC) for SSTR2 (ab134152, Abcam, 1:1000 dilution) to allow morphologic evaluation of tumor and normal tissues and to assess SSTR2 expression in the samples, respectively." (PMID 38267640, 2024). "In a blinded comparative interobserver study, we anonymized 47 patients with various tumors with SSTR2 expression and instructed four radiation oncologists to independently contour the macroscopic tumor volume using MRI alone and subsequently with the addition of DOTA-conjugated PET/CT." (PMID 38791956, 2024). "Additionally, fluorescent somatostatin analogs were used in order to delineate tumor boundaries for SSTR2-expressing tumors during surgery." (PMID 39329930, 2024). "Multiple tumor types feature frequent overexpression of somatostatin receptor type 2 (SSTR2)." (PMID 38791956, 2024). "In addition, SSTR2 expression levels (score 3+) in tumor tissue explained the reason why uptake of 18F-NOTA-JR11 increased in the lesions, increasing difficulty diagnosis." (PMID 39479016, 2024). "The identification not only of RET mutations in tumor tissue, but also of predictive indicators for the efficacy of PRRT, for example CCK2R and SSTR2 imaging, will likely be of great importance for the choice of the most appropriate therapy of MTC on an individual level." (PMID 38581480, 2024). "The metastatic tumor lesions also displayed a heterogeneous SSTR2 expression." (PMID 39324010, 2024). "In some types of tumor cells, the activation of SSTR2 can trigger apoptosis." (PMID 39329930, 2024). "The binding affinity of the peptides and the cellular uptake of 203Pb-labeled peptides were evaluated using pancreatic AR42J (SSTR2+) tumor cells and the biodistribution and imaging of the 203Pb-labeled peptides were assessed in an AR42J tumor xenograft mouse model." (PMID 37955792, 2024). "However, as well as being expressed on the surface of neuorendocrine tumour cells, SSTR2 is widely expressed in normal tissues, particularly of the endocrine system." (PMID 38543120, 2024).